TNF (tumor necrosis factor)
Diseases named in the same sentence as TNF in open-access papers (continued):
Sharing a sentence is not in itself a finding about the gene and the disease.
infection (continued). "In the BT group the synthesis of TNF-α by T-cells was significantly increased at day 7, rising again at days 28 and 42 for CD8+ T cells; this demonstrates that there is a preferred production of TNF-α by T cells in infection by BT forms." (PMID 22412949, 2012). "The levels of TNFα and IL10 were too low to be detectable at this dose of infection." (PMID 22719255, 2012). "The reduced level for IL-6, IL-1β, TNF-α, and IFN-γ in lung may be a reason for the enhanced morbidity in VK627 and rTsE627K infections." (PMID 22719870, 2012). "In a study using human volunteers infected with C. parvum, the expression of interleukin (IL)-1β and TNF-α in jejunal biopsies correlated with infection, but not with symptoms, while substance P levels did correlate with the severity of intestinal disease." (PMID 22685452, 2012). "Infection with the pathogenic Romero strain of JUNV has been reported not to induce measurable levels of IFN-β, IFN-α, TNF-α, IL-10 or IL12, in primary human monocytes and macrophages." (PMID 22629479, 2012). "However, in contrast to untreated animals, spleens of mice treated with LVF have significantly less TNF-α, IL-6, IFN-γ, MCP-1, and MIP-1α 4 days after infection." (PMID 22428026, 2012). "Six weeks after an aerosol infection, C3HeB/FeJ mice received standard TB treatment with or without adjunctive TNF inhibition (etanercept for the initial six weeks)." (PMID 22761866, 2012). "Similarly, mRNA levels for CD3, TNF-α, IFN-γ, iNOS, IL-10 and arginase I declined in WT spinal cords about the fourth or fifth week after infection, but kept increasing in IL-12p40KO mice." (PMID 23152844, 2012). "We find significant difference between the two groups regarding cytokine production for TNF-α at 24 h post-infection, but not for TGF-β1 and IL-10." (PMID 22574191, 2012). "In the present study, we demonstrate that SAV-3 infections induce mRNA transcripts of genes including IFN-α and its stimulated genes (ISG) at early time, followed by IFN-γ, TNF-α, IL-12, IL-10, IL-8, CD3ε, CD4, CD8, TCR-α, MHC-I, and MHC-II as the infection progresses." (PMID 23116479, 2012). "Mutants within iglA, iglC, iglG or iglI do not inhibit suppression of TNF-α secretion upon infection, suggesting that the FPI is crucial for this event." (PMID 22514651, 2012). "In contrast to the cytokine expression in WT mice, the expression of IL-1β and TNF-α in STAT3 KO mice was not longer raised 28 days after infection." (PMID 22675647, 2012). "Conversely, another study found that the severity of serious infections was not increased in anti-TNF-treated patients compared with a DMARD (disease modifying antirheumatic drugs)-treated cohort." (PMID 22405136, 2012). "Interestingly, DENV is able to trigger the expression of some proinflammatory cytokines (IL-6, IL-8, TNFα, and MIP-1β), a phenomenon observed at early times after infection." (PMID 22590678, 2012). "Results indicate that absence of Vpr decreased MDM infection over time and that reduced the expression of selective proinflammatory cytokines IL-1β, IL-8 and TNF-α in MDMs at the transcript and/or protein levels." (PMID 22727020, 2012). "We can therefore presume that H1N1pdm-induced apoptosis may be mainly attributed to FasL and TNF-α, while pig macrophages could be resistant to TRAIL, since the cells remained intact despite the presence of a high level of TRAIL before infection." (PMID 22279582, 2012). "TNF-α is the best characterized pro-inflammatory cytokine that is mainly secreted by macrophage, MCP-1 is a chemokine recruits monocytes, memory T cells, and dendritic cells to sites of tissue injury, infection, and inflammation." (PMID 22920325, 2012). "In addition to the cytotoxic role that CD8+ T lymphocytes play in the adaptive immune response during pathogen infection, they also simultaneously secrete some cytokines, such as IL-2, IFN-γ, and TNF-α." (PMID 22701633, 2012).
infection (continued). "During infection, NO is produced by inducible NO synthase (iNOS) in response to bacterial components or a combination of proinflammatory cytokines, such as interferon (IFN)-γ, TNF-α, and IL-1β." (PMID 22851964, 2012). "Moreover, tumour necrosis factor (TNF)-α plays a key role in the pathogenesis of RA, and the propensity of anti-TNF-α agents to facilitate infection in patients with RA is a source of concern." (PMID 22925480, 2012). "Th1 CD4+ cells confer immunity to infection by intracellular pathogens through production of effector cytokines IFN-γ, Il-12, TNF, and IL-2, while Th2 CD4+ cells promote the clearance of multicellular helminths and ectoparasites by producing IL-4, IL-5 and IL-10." (PMID 22685452, 2012). "Compared to the infected wild-type mice, the mRNA expression levels of IL-1β, IL-6, and TNF-α as well as the number of infiltrating immune cells revealed no distinction in STAT3 KO mice 10 days after infection." (PMID 22675647, 2012). "Moreover, the ratio of TGF-β1/TNF-α and of IL-10/TNF-α production were higher in DCL than LCL isolates at 24 h post-infection." (PMID 22574191, 2012). "We also observed high levels of TNF-α and MCP-1 in the plasma on day 6-post infection (TNF: 106.1±22.1 pg/mL in uninfected, 855.9±262.6 pg/mL in PbA-infected animals; MCP-1, 342.2±100.2 pg/mL in uninfected, 1189±275.6 pg/mL in PbA-infected animals; p<0.05 by Mann-Withney test in each case)." (PMID 23300448, 2012). "Our results show that phox KO mice exhibited no immune impairment, producing equivalent amounts of IFN-γ and TNF in response to infection and presenting similar histopathology (data not shown) to their WT partners." (PMID 22348160, 2012). "HCs were pretreated with or without IL-10, TGF-β, IL-4, IL-6, IFN-γ, and TNF-α prior to infection with HIV-1BaL." (PMID 23217137, 2012). "Additionally, we found that the higher intrathymic TNF-α contents inversely correlated with the thymic relative weight and the relative numbers of CD4+CD8+ cells, thymic parameters that declined along infection." (PMID 22461911, 2012). "It has been reported that in cattle experimentally infected with M. bovis the expression of IFN-γ, TNF-α, iNOS and IL-4 by PBMCs increase in response to infection, andthat animals with high pathology express more IFN-γ, TNF-α, iNOS and IL-4 than animals with low pathology." (PMID 23251517, 2012). "Further, IL-6 and IL-10 production were shown to be dependent on productive infection, while TNF-α production was not." (PMID 21572983, 2011). "M. tuberculosis infection is known to induce TNF-α production, but in vivo, infection of host cells does not occur in a vacuum, but in the presence of a variety of immunomodulating factors." (PMID 21253484, 2011). "In the absence of TNF, increased apoptosis was delayed until 7 days post infection, and remained significantly higher than observed in WTs at 10 days." (PMID 21269505, 2011). "Macrophage apoptosis induced by a high MOI-infection with virulent Mtb does not require TNF-α, caspases, or Toll signals but culminates in macrophage necrosis." (PMID 22194844, 2011). "Here, we show that the transmigration of PMNs through PCPECs was significantly higher after stimulation with TNFα or infection with S. suis strain 10 compared to its non-encapsulated mutant." (PMID 21592385, 2011). "The sub-dominant epitopes not only failed to elicit IFN-γ and in vivo cytotoxicity during infection, but they also did not stimulate TNF-α, IL-2 or IL-10 secretion by CD8+ T cells." (PMID 21779365, 2011). "Interestingly, infection induced a substantial expansion of TNF-α single positive cells and IL-2/TNF-α double positive cells." (PMID 21720558, 2011). "The fact that the inhibitory effect of TNF-α was observed only when cultures were pre-incubated with the cytokine suggested that stimulated hepatocytes secrete an inhibitory factor and/or that the TNF-α treatment makes them refractory to infection." (PMID 21394207, 2011).
infection (continued). "Patients with PB disease present very low bacterial counts, exhibiting localized infection and lesions characterized by expression of type 1 (TH1) T helper lymphocyte-related cytokines (cell-mediated immunity) as IL-2, IL-6, IL-12, IFN-γ, and TNF." (PMID 22220182, 2011). "Higher TNF-alpha levels were produced by seronegative individuals without stimulation, indicating that individuals who did not acquire the infection are able to produce TNF-alpha spontaneously." (PMID 21408088, 2011). "RELM-β−/− mice infected with a Th1-inducing low dose T. muris infection express significantly less IFN-γ and TNF-α in the gut than control mice, fail to induce intestinal inflammation and do not sustain infection." (PMID 21392042, 2011). "TNF-alpha genotypes found in subjects from an endemic area according to the presence or absence of infection." (PMID 21408088, 2011). "Furthermore, expression of several key host defense genes, including cytokines (TNFα and IL6) and bactericidal molecules, such as defensin-4 (NP4), NOS2, NOX1 and ICAM1, peaked only at 8 and/or 12 weeks post-infection." (PMID 22645653, 2011). "At 4 weeks post-infection, low basal levels of expression of TNF-α and PDE4A were noted in comparison with uninfected animals." (PMID 21949656, 2011). "After 9 h of incubation, TNF-α-induced NF-κB activity was also deceased upon infection with the invasive isolate LNP19995 but not with the carriage isolate LNP21019." (PMID 22144896, 2011). "We found that the conidia bound to macrophages in a dose-dependent fashion, yet surprisingly failed to stimulate the production of TNF, even at high multiplicities of infection (moi)." (PMID 21575914, 2011). "In particular, the neutralization of IL-27 by soluble receptor has been shown to augment the levels of TNF-α and IFN-γ during early infection and may allow macrophages to better combat Mtb at a critical time." (PMID 21197399, 2011). "We observed that no TNF-α was secreted into the media 16 h post-infection under both static and shear conditions." (PMID 21249123, 2011). "AUC analysis did not reveal statistically significant differences in milk TNF-α concentrations between persistent and spontaneously eliminated infections." (PMID 21414189, 2011). "We had also determined by ELISA and Reverse Phase protein MicroArray (RPMA) that there was an increase in TNFα protein expression following MP12 infection (data not shown)." (PMID 21655261, 2011). "TNF-α mRNA levels increased to about 30- and 45-fold, respectively, in response to 8 and 12 weeks of infection, but were not significantly different between these two time points." (PMID 21949656, 2011). "Since the natural route of infection for Salmonella is via the oral route we also determined the impact of infection with S. Typhimurium C5507 Vi+ and SGB1 Vi− on intracellular production of MIP-2, TNF-α, IFN-γ and perforin by immune cells of the MLNs 24 h post inoculation." (PMID 21829346, 2011). "Cell-mediated host immunity to infection is characterized by immune cell activation and secretion of cytokines, including gamma interferon (IFN-γ), IL-12, IL-18, IL-23 and tumor necrosis factor alpha (TNF-α)." (PMID 21698225, 2011). "Myr+ recNef treatment of primary MDMs as well as infection of MDMs with nef espressing HIV-1 pseudotypes induces the synthesis and the release of several inflammatory cytokines and chemokines (i.e. IL-1β, IL-6, TNFα, MIP-1α and MIP-1β)." (PMID 21886773, 2011). "On the other hand, and similar to B6 animals, AKR/J mice had undetectable levels of IL-10 even 48 h post-infection and no statistically significant increase in concentrations of IL-6, TNF-α, MCP-1 or KC." (PMID 21533108, 2011). "In the pathogenesis of carcinogenesis, pro-inflammatory cytokines such as interleukin-1α (IL-1α), tumor necrosis factor (TNFα), and regulated upon activation, normal T cell expressed and secreted (RANTES), can regulate host responses to infection, inflammation and various immune responses." (PMID 21320340, 2011).
infection (continued). "While, generation of effector cytokines, such as IFNγ and TNFα by the Th1 cells are known to be crucial for the resolution of M. tuberculosis infection, IL2 production by these T helper cells aids in the maintenance of memory immunity against infection." (PMID 21533158, 2011). "In this study, we demonstrated that a TNF-dependent cytokine network involving M.tb-infected monocytes, but not direct infection by M.tb, down-regulates MMP-2 secretion from microglial cells via p38 MAP kinase, NFκB and caspase 8 pathways." (PMID 21569377, 2011). "The levels of CD4 cells producing IFN-γ, IFN-γ/TNF-α, or IFN-γ/TNF-α/IL2 all exceeded 1% in BCG vaccinated mice at week 2 of the P. yoelii infection (10 weeks post-BCG immunization) but declined at weeks 7 and 10 post-infection (15 and 18 weeks post-BCG vaccination)." (PMID 22205939, 2011). "All this agrees with our results, considering that the expression of TNF-α was not induced by M. paratuberculosis, while it was stimulated after the infection of both cell lines by M. tuberculosis and M. bovis." (PMID 22151930, 2011). "Consistent with previous findings, Tir was not required for EPEC to inhibit TNFα-induced NF-κB activation though infection studies revealed a small, but statistically significant inhibitory defect for a Tir-deficient strain." (PMID 22144899, 2011). "In this context it is particularly relevant that in a subset of AD patients there was evidence of elevated TNF-α, in the absence of detected infection, and these patients also showed accelerated decline." (PMID 21586125, 2011). "Meanwhile, TNF-α and IL-8 were expressed at >10 folds in H5N1/2004 infection." (PMID 21108843, 2010). "However, to our surprise, we found that upon infection with T. gondii, except for impaired IL-12p40 production, 3d mice showed high levels of IL-6, MCP-1, IFNγ, and TNFα in their sera." (PMID 20865117, 2010). "Upon infection, stimulation of TLRs or the cytosolic NOD1 or NOD2 receptors activates transcription, synthesis, and secretion of pro-inflammatory cytokines such as INFγ, IL-12, and TNFα." (PMID 20368800, 2010). "To test this hypothesis, we measured the concentrations of TNF-α and IL-1β in the bronchiolar alveolar lavage fluid (BALF) after IN infection with CO92 or CO92ΔyopH." (PMID 20565713, 2010). "A549 were chosen as APCs because they do not produce tumor necrosis factor-α (TNF-α) in response to infection with Mtb, nor elicit an allogeneic response by polyclonal CD8+ T cells isolated from the periphery and lung (and unpublished data)." (PMID 20613858, 2010). "Similarly for H9N2/1997 infection, there was 5-25 folds increase in the transcription of CCL-5/RANTES, TNF-α, and CXCL-10/IP-10 mRNA at 3 hours post-infection." (PMID 21108843, 2010). "However, when the isogenic TNF-α-/- mice were infected with 2 × 104 CFU CO92ΔyopH, significantly (p = 0.0289), 40% of the mice succumbed to infection within 5 days." (PMID 20565713, 2010). "Specifically, we compared the induction of several pro-inflammatory cytokines (TNFα, IL6, IFNγ and MCP1) for changes in expression during infection by analyzing lung homogenates by CBA or quantitative RT-PCR to measure levels of mRNAs in Urbani virus or rMA15 virus infected mice, respectively." (PMID 20386712, 2010). "While oscillations have been shown in response to TNFα, the topoisomerase II inhibitor etoposide and LPS they have not yet been investigated during infection with live bacteria." (PMID 20233427, 2010). "Our experiments had revealed that 16 hours after infection, the epidermis in resistant C57BL/6 mice is a major and stronger source not only for chemokines, but also for cytokines known to have the potential to induce Th1 cells (IL-12, IL-1β, TNFα and opn)." (PMID 20442861, 2010). "It had an average intracellular growth rate and did not control TNF-α levels at early stages of the infection." (PMID 20500810, 2010).
infection (continued). "Rather than determining the course of infection, TNF levels appear to reflect the burden of infected macrophages in our mouse model." (PMID 20950462, 2010). "While we were able to detect higher TNF-α secretion in SphK-1++ infected macrophages over WT infected macrophages at 1 h post infection, this remained insignificant (data not shown)." (PMID 20498849, 2010). "Our data suggest that the CD4pos T-cell response against CMV is not altered by anti-TNF-α treatments and that infection remains controlled in treated RA patients latently infected with CMV." (PMID 20633267, 2010). "In patients receiving TNFα-blockers, TJA infection is rare but potentially severe." (PMID 20637100, 2010). "In all cases, the infection by MTB increased the TNF-α production compared to the values observed in the non-infected control." (PMID 20500810, 2010). "It is noteworthy that IL-10 levels were maintained close to the basal level among infected animals on the 7th and 21st days p.i., while pro-inflammatory cytokine levels (TNF-α, CCL2, IL-6 and IFN-γ) presented a great variation among different experimental groups during the acute phase of infection." (PMID 20967289, 2010). "However, by day seven post-infection this difference inverted, and mice infected with 124A presented significantly higher levels of IFN-γ and TNF." (PMID 20405013, 2010). "The use of TNF-α-neutralizing antibodies and specific caspase inhibitors on human macrophage cell lines, as well as the infection of bone-marrow derived macrophages (BMDM) of wild-type and TNF−/− mice demonstrated that NuoG is involved in inhibiting an extrinsic, TNF-α-dependent, apoptosis pathway." (PMID 20421951, 2010). "The BALF samples did not contain detectable levels of TNF-α and IL-10, independent of infection time." (PMID 19383119, 2009). "On the other hand, the pro-inflammatory chromatin binding protein, HMGB1, was detected as early as 2 h after infection in the supernatant of the IFNγ-induced, T. gondii infected cells but not in the supernatants of the cycloheximide and TNFα-treated cells." (PMID 19197351, 2009). "Notable also was the complete lack of detectable TNF in the lungs of the MyD88−/− mice at days 1–5 post-infection." (PMID 19936231, 2009). "After vaccination, infection induced a large increase in expression of IFN-γ especially on days 1 and 8 p.i., whereas vaccination dampened the infection-induced increases in mRNA levels for the proinflammatory cytokines IL1-β, TNF, and IL-6 – in particular around peak parasitaemia." (PMID 19341445, 2009). "The levels of TNF-α, IL-1β and IL-6 in BAL before infection were similar in both groups." (PMID 19835595, 2009). "Between 20% and 40% of pDC in blood produced TNF-α in response to TLR7 stimulation regardless of infection status." (PMID 19424421, 2009). "TNF and IL-12 concentrations did not change during the course of infection and remained at the level found in non-infected control mice." (PMID 19508725, 2009). "Unlike the case of IL-10, infection with T. gondii inhibited TNF-α production during LPS and LPS + IC stimulation to background levels." (PMID 19859561, 2009). "GML suppressed TNF-α at the infection site on day 7; however, DDG did not (<10 ng/ml versus 80 ng/ml, respectively)." (PMID 19838303, 2009). "There was a high variation among the individuals tested at both time points, but no significant change in the TNF-α production with respect to infection time for any of the four breeds." (PMID 19383119, 2009). "This increase might also play a role in vivo, since in situ hybridisation studies following a natural infection with A. pleuropneumoniae showed positive signals for NOS2 and TNF-α in alveolar macrophages." (PMID 19383119, 2009).